IGHV1-2 (immunoglobulin heavy variable 1-2)
Description:
V region of the variable domain of immunoglobulin heavy chains that participates in the antigen recognition. Immunoglobulins, also known as antibodies, are membrane-bound or secreted glycoproteins produced by B lymphocytes. In the recognition phase of humoral immunity, the membrane-bound immunoglobulins serve as receptors which, upon binding of a specific antigen, trigger the clonal expansion and differentiation of B lymphocytes into immunoglobulins-secreting plasma cells. Secreted immunoglobulins mediate the effector phase of humoral immunity, which results in the elimination of bound antigens. The antigen binding site is formed by the variable domain of one heavy chain, together with that of its associated light chain. Thus, each immunoglobulin has two antigen binding sites with remarkable affinity for a particular antigen. The variable domains are assembled by a process called V-(D)-J rearrangement and can then be subjected to somatic hypermutations which, after exposure to antigen and selection, allow affinity maturation for a particular antigen.
Synonyms: V35; IGHV12
Tractability: Antibody: UniProt places it where antibodies can reach, with medium confidence; UniProt predicts a signal peptide or a membrane-spanning region; its Gene Ontology location is reachable by antibodies, with medium confidence.
Gene: Immunoglobulin variable (V) gene on chromosome 14 (105,986,582 to 105,987,083, reverse strand). Ensembl gene ENSG00000211934.
Subcellular location: Secreted; Cell membrane
Pathways (Reactome):
Immune System: Antigen activates B Cell Receptor (BCR) leading to generation of second messengers; CD22 mediated BCR regulation; Classical antibody-mediated complement activation; FCERI mediated Ca+2 mobilization; FCERI mediated MAPK activation; FCERI mediated NF-kB activation; FCGR activation; Fc epsilon receptor (FCERI) signaling; Immunoregulatory interactions between a Lymphoid and a non-Lymphoid cell; Initial triggering of complement; Regulation of Complement cascade; Regulation of actin dynamics for phagocytic cup formation; Role of LAT2/NTAL/LAB on calcium mobilization; Role of phospholipids in phagocytosis
Disease: FCGR3A-mediated IL10 synthesis; FCGR3A-mediated phagocytosis; Potential therapeutics for SARS
Hemostasis: Cell surface interactions at the vascular wall
Vesicle-mediated transport: Scavenging of heme from plasma
Gene Ontology:
Molecular function: antigen binding
Biological process: immune response; immunoglobulin mediated immune response
Cellular component: extracellular region; plasma membrane
Homologues: Orthologues: mouse Ighv1-53 (71% identical), mouse Ighv1-64 (71% identical), mouse Ighv1-50 (70% identical), mouse Ighv1-74 (70% identical), mouse Ighv1-55 (69% identical), mouse Ighv1-69 (68% identical), mouse Ighv1-72 (68% identical), mouse Ighv1-4 (67% identical), mouse Ighv1-59 (67% identical), mouse Ighv1-66 (67% identical), mouse Ighv1-52 (66% identical), mouse Ighv1-61 (66% identical), and 47 more. Paralogues in human: IGHV1OR15-1 (91% identical), IGHV1-3 (88% identical), IGHV1-18 (86% identical), IGHV1-46 (85% identical), IGHV1-45 (81% identical), IGHV1-24 (80% identical), IGHV1-69 (79% identical), IGHV1-69D (79% identical), IGHV1-58 (78% identical), IGHV1-69-2 (77% identical), IGHV1OR21-1 (77% identical), IGHV7-4-1 (77% identical), and 65 more.
Diseases named in the same sentence as IGHV1-2 in open-access papers:
IGHV1-2 is named in the same sentence as 2 diseases in open-access papers, as found by Europe PMC text mining. Sharing a sentence is not in itself a finding about the gene and the disease. The quoted sentences say what the papers report.
infection (1 paper, 2022). The state of being infected such as from the introduction of a foreign agent such as serum, vaccine, antigenic substance or organism. "Furthermore, the XJ strain infection group specifically expressed IGHV8-12-IGHJ1, IGHV12-3-IGHJ4 and IGHV1S134-IGHJ4 genes, while the Bartha-K61 strain infection group specifically expressed IGHV1-12-IGHJ1, IGHV1-22-IGHJ1, IGHV1-50-IGHJ2 and IGHV1-30-IGHJ3." (PMID 35715782, 2022). "The XJ strain infection group expressed IGHV8-12-IGHJ1, IGHV12-3-IGHJ4 and IGHV1S134-IGHJ4 genes, but did not express IGHV1-12-IGHJ1, IGHV1-22-IGHJ1, IGHV1-50-IGHJ2 and IGHV1-30-IGHJ3 genes in comparison with Bartha-K61 strain infection." (PMID 35715782, 2022).
IGHV1-2 also shares sentences with these, for which no sentence is quoted: diabetic mellitus type 2 (1 paper).